MYBPHL (myosin binding protein H like)
Description:
Myosin-binding protein which plays a role in cardiac function. Seems to regulate conduction in the atria and ventricular conduction systems.
Tractability: No criterion of Open Targets' tractability assessment is met for any kind of drug.
Gene: Protein-coding gene on chromosome 1 (109,292,363 to 109,307,213, reverse strand). Ensembl gene ENSG00000221986.
Subcellular location: Cytoplasm, myofibril, sarcomere
Subcellular location (Human Protein Atlas): Vesicles
Gene Ontology:
Molecular function: protein binding
Cellular component: myofilament; sarcomere
Genetic constraint (gnomAD): Loss-of-function variants: 32 observed, 40.54 expected, observed/expected ratio (o/e) 0.79, 90% interval 0.6 to 1.06. The upper end of that interval is the gene's LOEUF score, 1.06, which puts it in group 4 of 6, group 1 being the genes least tolerant of losing a copy. Missense variants: 454 observed, 478.35 expected, observed/expected ratio (o/e) 0.95, 90% interval 0.88 to 1.03. Synonymous variants: 195 observed, 193.12 expected, observed/expected ratio (o/e) 1.01, 90% interval 0.9 to 1.14.
Homologues: Orthologues: chimpanzee MYBPHL (99% identical), macaque MYBPHL (98% identical), pig MYBPHL (90% identical), rabbit MYBPHL (90% identical), guinea pig MYBPHL (87% identical), dog MYBPHL (85% identical), rat Mybphl (85% identical), mouse Mybphl (83% identical), Caenorhabditis elegans C34F6.10 (17% identical), Drosophila melanogaster mtgo (14% identical). Paralogues in human: MYBPH (68% identical), MYBPC1 (50% identical), MYBPC3 (47% identical), MYBPC2 (47% identical), IGSF22 (25% identical), MYOM3 (23% identical), MYOM1 (22% identical), MYOM2 (22% identical), OBSL1 (19% identical), FNDC3A (18% identical), FNDC3B (17% identical).
Diseases named in the same sentence as MYBPHL in open-access papers:
MYBPHL is named in the same sentence as 16 diseases in open-access papers, as found by Europe PMC text mining. Sharing a sentence is not in itself a finding about the gene and the disease. The quoted sentences say what the papers report.
neuropathy (3 papers, 2024 to 2025). A disorder affecting the nervous system that manifests with pain, tingling, numbness, and/or muscle weakness. "The rs604349 is an intronic SNP in MYBPHL (myosin-binding protein H-like) gene that seems to aggravate the risk for neuropathy." (PMID 38928135, 2024). "rs604349 is an intronic SNP in the MYBPHL (myosin binding protein H like) gene that seems to aggravate the risk of neuropathy." (PMID 38339094, 2024). "At this time, rs604349 in MYBPHL and rs2032930/rs2032931 in the RMI2 gene appear to be of importance in increasing the risk for developing neuropathy, while rs917778 in MVB12B and rs2234753 in the RXRA gene might reduce the likelihood of this complication." (PMID 38928135, 2024).
atrial fibrillation (1 paper, 2019). A disorder characterized by an electrocardiographic finding of a supraventricular arrhythmia characterized by the replacement of consistent P waves by rapid oscillations or fibrillatory waves that vary in size, shape and timing and are accompanied by an irregular ventricular response. "Therefore, we analyzed MYBPHL protein concentration in the plasma from 17 patients undergoing surgical cryo- or radiofrequency ablation for atrial fibrillation." (PMID 31292467, 2019). "Furthermore, we provide evidence that an induced atrial damage by cryo- or radiofrequency ablation procedures in patients suffering from atrial fibrillation provokes a rapid, time-dependent and long-lasting release of MYBPHL into the plasma." (PMID 31292467, 2019).
diabetic neuropathy (1 paper, 2024). A chronic, pathological complication associated with diabetes mellitus, where nerve damages are incurred due to diabetic microvascular injury involving small blood vessels that supply these nerves, resulting in peripheral and/or autonomic nerve dysfunction. "We successfully identified three genetic variants (rs2032930 and rs2032931 of the RMI2 gene and rs604349 of the MYBPHL gene) which were associated with a 22–49-fold increase in the risk of developing diabetic neuropathy." (PMID 38339094, 2024).
lung adenocarcinoma (1 paper, 2024). A carcinoma that arises from the lung and is characterized by the presence of malignant glandular epithelial cells. "In lung adenocarcinoma cells, MYBPHL interacts with Rho kinase 1 to inhibit RLC phosphorylation on NM IIA." (PMID 39273383, 2024). "MYBPHL interacts with the rod domain of the NM IIA heavy chain to inhibit the assembly and reduce the motility of lung adenocarcinoma cells." (PMID 39273383, 2024).
multiple myeloma (1 paper, 2021). "Even though enhancer landscapes are considered to be cell-specific, we clearly showed that the interaction of the MYBPHL enhancer-promoter pair in myeloma plasma cells is consistent with the previous report in HCC18." (PMID 33772052, 2021). "Enhancer DNA methylation and expression of MYBPHL was studied in multiple myeloma (MM)." (PMID 33772052, 2021).
pituitary adenomas (1 paper, 2025). "Additional genes—PHYHD1, LTBR, MYBPHL, C22orf42, PRR5, ANKDD1A, RAB13, CAMKV, KIFC3, WNT4, and STAT6—were implicated in the invasive behavior of non-functioning pituitary adenomas (NFPAs)." (PMID 39859246, 2025).
cancer (1 paper, 2015). A tumor composed of atypical neoplastic, often pleomorphic cells that invade other tissues. "A further large-scale mutation of interest was identified from a split read in the Complete Genomics data between chr1:27,080,702 (intron 16 of ARID1A) and chr1: 109,834,252 (close to MYBPHL) in cancer P13." (PMID 25790038, 2015).
cardiac disease (1 paper, 2019). "The understanding of the potential role of MYBPHL in cardiac disease is very limited." (PMID 31292467, 2019).
cardiovascular disease (1 paper, 2019). "Furthermore, serum MYBPHL levels are similar between healthy volunteers and pre-operative values from patients suffering from cardiovascular disease." (PMID 31292467, 2019).
tumor (1 paper, 2019). "The DNA methylation and expression levels of PHYHD1, LTBR, MYBPHL, C22orf42, PRR5, ANKDD1A, RAB13, CAMKV, KIFC3, WNT4 and STAT6 are associated with tumor invasion, and these genes may become the potential genes for targeted therapy." (PMID 31796052, 2019).
MYBPHL also shares sentences with these, for which no sentence is quoted: cardiac hypertrophy (1 paper); cleft lip (1); dilated cardiomyopathy (1); hepatocellular carcinoma (1); hypospadias (1); type 2 diabetes (1).